MIR5571 (microRNA 5571)
Synonyms: hsa-mir-5571
Gene: MicroRNA gene on chromosome 22 (22,886,267 to 22,886,379, forward strand). Ensembl gene ENSG00000264824.
Homologues: Orthologues: chimpanzee MIR5571 (100% identical).